CD69 (CD69 molecule)
Diseases named in the same sentence as CD69 in open-access papers (continued):
Sharing a sentence is not in itself a finding about the gene and the disease.
tumor (continued). "Moreover, Met@Man-MPs significantly enhanced the numbers of CD8+ T cells, activated CD8+CD69+ T cells, CD4+ T cells, and activated CD4+CD69+ T cells, while markedly decreased the numbers of MDSCs and Tregs in tumor tissues compared with free Met, Met@MPs and even high dosage of Met." (PMID 33469052, 2021). "In NSCLC, activation of tissue-resident NK cells were reported to have an exhausted phenotype (CD69 + CXCR6+), highlighting their noncytotoxic function resulting in poor anti-tumor immunity." (PMID 40849493, 2025). "PD-1 expression, but not CD69 expression, was significantly enhanced on CD4+ T cells in the treated tumor." (PMID 39410025, 2024). "As expected, the vast majority of SIINFEKL+ CD8+ T cells in the tumor expressed CD69 and lacked CD62L, with a fraction of CD69+ cells co‐expressing CD103, a marker associated with tissue residency that is lacking on circulating CD44+ T cells." (PMID 39584189, 2024). "Upon contact with UM-UC-3 and MG-63 tumor cells, VAR2-[SpyT][SpyC]-CAR T cells, but not unarmed [SpyC]-CAR T cells, upregulated the activation markers CD25 and CD69." (PMID 39406935, 2024). "ZFP36 KO did not alter antigen-induced CD25 and CD69 expression in CD4 or CD8 mesoCAR-T cells, nor did it change the percentage of CD25+ CD69+ cells without tumor cells." (PMID 38326511, 2024). "The unexpected absence of CD69 and CD25 in C002-induced CD4(+) T cells raises questions about the optimal time for conducting immunophenotyping of tumor infiltrates to capture the nuanced changes in T cell activation." (PMID 38895115, 2024). "Within tumor-specific i.e. tetramer double positive CD8 T cells, we find that the majority were terminally differentiated (CD39+CD69+), which did not vary across TME checkpoint conditions." (PMID 37359554, 2023). "The lack of very early, TCR-driven activation markers such as CD69 and CD25 in the irradiated tumor also argues against nascent antigen-specific T cell activation in the untreated tumor." (PMID 37209684, 2023). "Following an ex vivo 6-h co-culture of lung and spleen cells with viable 4T1 tumor cells, we observed a significantly (p ≤ 0.05) higher proportion of both CD8+ CD69+ CD44hi and CD4+ CD69+ CD44hi T cells from the lungs but not spleen." (PMID 36839766, 2023). "Further, markers of nascent, antigen-specific activation such as CD69 and CD25 were not expressed among tumor-infiltrating T cells in the irradiated tumor, arguing against their priming in the irradiated tumor at this time interval after radiation." (PMID 37209684, 2023). "Despite being less frequently found in the tumor and ascites, NK cells in tumors displayed significantly increased expression of activating markers such as NK1.1, NKp46, and CD69, but not LAG3 nor NKG2D." (PMID 38235131, 2023). "The CD8+ CD103+CD69+ TRM subset was represented within both NT and tumor sites, while found at low frequency or absent in CD8+ T cells isolated from the periphery." (PMID 37898752, 2023). "Again, tumor and blood Tregs showed the most important difference with 8% and 80% of cells that did not express any of CD38, CD40L, CD69, and GITR molecules, respectively." (PMID 36566320, 2022). "In the present study, we explored the effect of DNA methylation on the expression of the genes related to the non-coding RNAs but found no significant methylation of CD69, IL7R, and PTPRC in tumor tissues compared with that of normal tissues." (PMID 36032150, 2022). "Flow cytometric analysis after 6 d of treatment showed that IRE1α inhibition increased tumor infiltration by cytotoxic CD8+ T cells and their expression of the activation markers IFN-γ, PD-1, and CD69, independent of IRE1α status in the malignant cells." (PMID 35446348, 2022). "In line with a potentially more “silenced” phenotype, these nonlesional tumor cells harbored elevated levels of CXCR4, CD69, HSPA1A, ZFP36, IL7R and TXNIP when compared to matched lesional skin." (PMID 34583709, 2021).
tumor (continued). "In experiment with CEA‐negative tumor cells as target cells, the expression levels of CD25 and CD69 had no significant changes among the four treatment conditions." (PMID 31237116, 2019). "Expression of T-cell activation markers, CD69, ICOS and TIGIT, on tumor-infiltrating T-cells was not affected." (PMID 31747946, 2019). "DP T cells expressed ITGAE (codes for CD103), and CD69, but not SELL, KLF2, and S1PR1, suggesting a tumor resident phenotype." (PMID 30534127, 2018). "Recently, a new subset of CD4+ Tregs that primarily express CD4 and CD69, but not CD25, has been identified in a tumor-bearing mouse model." (PMID 24984576, 2014). "Preliminary experiments showed that supernatants from tumours treated with any of the drugs had no direct effect on the numbers and/or activation states of NKs (CD3−, CD69+, CD56+ and CD16+), T cells (CD3+, CD25+ and CD69+) and T-regs (CD4+, CD25+ and Foxp3+)." (PMID 19997099, 2010). "Furthermore, there was no notable distinction in the CAR-T cell activation marker, CD69, between the RSL3-treated and untreated groups following the co-culture with tumor cells." (PMID 39849645, 2025). "Disruption of ZFP36 in CD4 mesoCAR-T cells cocultured with antigen-negative tumor cells led to a statistically significant, slight increase in CD25+ CD69+ population; however, this difference was notable only in one of three donors and is not a strong phenotypic difference." (PMID 38326511, 2024). "Of course, CD69 may not act alone; GSEA data revealed that T-αFGL2 cells, when cocultured with tumor cells, exhibited decreased expression of circulation-associated genes." (PMID 36759517, 2023). "In addition, knockout of NOXA in tumor cells did not alter CAR T-cell-activated phenotype, as indicated by the markers CD25 and CD69 or the memory phenotype measured by markers CD45RO and CD62 L after 24 h of coculture." (PMID 35370290, 2022). "Additionally, both expression levels of CD69 and PD1 in tumor-infiltrating CD8+ T cells showed no marked difference among PBS, oAd-ctr or oAd-mCD47nb-Fc-treated mice." (PMID 35837100, 2022). "However, both CD39 and PD-1 are also expressed by regulatory CD4+ T cells (Tregs), and CD69, rather than CD103, is a marker of tumor residency in CD4+ T cells." (PMID 36003398, 2022). "However, the increased prevalence of CD3−/CD94+/CD69+ NK cells in the circulation of NSCLC patients in stages III and IV compared to the healthy controls did not result in improved tumor control." (PMID 36428793, 2022). "We observed a small increase in the early (CD69) but not late (CD25) T cell activation confirming the reduction in the viability was due to non-specific activation of T cells when cocultured with oHSV-1 and tumor cells." (PMID 33820820, 2021). "Interestingly, expression of the early activation marker CD69 appears to be independent of epitope density, and similarly CD69 and PD1 can be induced in the tumor environment independent of cognate antigen." (PMID 33968757, 2021). "In addition, the expression of BTG2, CD69, GPC3, and IL7R were considerably elevated in tumor stages III-IV as opposed to tumor stage I-II (p < 0.05)." (PMID 34881236, 2021). "However, after stopping osimertinib injection of IVT4 not only inhibited outgrowth of the tumor compared to the non-specific control IVT-GAC but led to a further reduction in tumor volume and a lower rate of TIM3+/PD-1+CD69− CD8 cells with osi pre-treatment." (PMID 34535668, 2021). "In contrast, in the OV2944-HM-1 model, which was insensitive to anti-PD-L1 mAb treatment, expression of CXCR3 ligands in the tumor was lower than that in the FM3A model and we confirmed that anti-PD-L1 mAb treatment increased the number of CD69+CD8α+ T cells in lymph nodes but not in tumors." (PMID 34230534, 2021). "CD69 and CD25 were also upregulated by BiTE in the absence of PDL1+ tumor cells." (PMID 28938530, 2017).
tumor (continued). "ICI therapy did not affect the density of CD69+ activated lymphocytes, Perforin+ activated CD8+ T cells, PD-1+ cells or number of cells staining positively for an antibody specific to cleaved-Caspase 3 to assess the extent of potential immune-mediated apoptosis of tumour cells." (PMID 40473819, 2025). "However, CD69, CD73 or Ki-67 staining of CD19+ B cell follicles did not indicate increased germinal center formation or activity in the lymph nodes upon combination therapy compared with other groups of tumor-bearing mice." (PMID 40897896, 2025). "Moreover, the tumor as well as the adjacent, nontumoral tissue displayed the increased presence of T cells featuring the Trm markers CD69 and CD103 (CD8+ C6, C7, and C8) or CD69 only (CD4+ C1 and C7), hereafter referred to as Trm." (PMID 34552178, 2021). "However, these tumor-infiltrating CD8+ T lymphocytes exhibited a highly activated phenotype (upregulated CD25, CD44, and CD69 and down-regulated CD62L expression) but lacked effector cell function, measured by a killing assay, suggesting modulation of the CD8+ T lymphocytes by the tumor environment." (PMID 32733446, 2020). "Interestingly, tumor sizes from MRI data on the day prior to tracer injection, between doses on ICI, did not correlate with either survival or CD69 SUV signals in the ICI-treated group, and MRI on day 6 could not provide evidence of difference between the treatment groups." (PMID 37426447, 2023).
infection (416 papers, 2007 to 2026). The state of being infected such as from the introduction of a foreign agent such as serum, vaccine, antigenic substance or organism. "For double-positive SKOV3 cells, infection with all TCE-encoding oAds viruses led to a significant increase of CD69 surface expression of both CD4+ and CD8+ T cells compared to the control virus." (PMID 41552759, 2026). "Although the infection-associated changes in AT T cell proportions were limited, we also analyzed the expression of standard T cell markers (such as PD-1 and CD69) and other markers of cell activation and proliferation." (PMID 35661814, 2022). "The susceptibility to infection was determined in both CD69+ and CD69− T cells, which revealed that CD69+ T cells are less inclined to get infected with DENV in comparison to CD69− cells." (PMID 36423184, 2022). "We reported that all the cells infected in the intestine in very early SIV infection were CD4+CD69+ cells and that the selective loss of CD69+ cells occurred in the blood in very early infection." (PMID 34960667, 2021). "Infection of unvaccinated mice was associated with an increase in the frequency of activated (CD69+) T cells in the lung (p = 0.006); this was attenuated by vaccination (p < 0.001) and increased by depletion of NK cells." (PMID 32117282, 2020). "This showed that blood-stage infection caused T cell activation in the spleen, although some CD69 up-regulation was observed in liver-draining lymph nodes (portal and celiac LNs)." (PMID 24854165, 2014). "In this model, loss of N1 promotes a stronger NK cell response to infection but there are fewer CD69+ cells." (PMID 18931086, 2008). "In vitro Puumala orthohantavirus infection of PBMC caused MAIT cell CD69 upregulation, and infection of MAIT cells in co-culture with the monocyte cell line THP-1 induced upregulation of CD69, CD38 and CD25, as well as the markers of cytolytic capacity perforin, granzyme B and CD107a." (PMID 35381137, 2021). "Notably, NK cells from skin blister fluid expressed high levels of CD69 during the acute phase of the infection, a marker that has recently been associated with lymphocyte tissue residency." (PMID 31467285, 2019). "Furthermore, failure to clear infection at 21 dpi was associated with a lower number of total and activated CD69+ CD4+ T cells in infected mice than in control and/or infected mice at 7 dpi (P < 0.0001 and P = 0.03, respectively)." (PMID 29610255, 2018). "Moreover, secondary antigen stimulation caused CD8+ T cells to rapidly express CD69 and be retained at the site of infection." (PMID 28523003, 2017). "After RH and ME49 infections, CD69+ cNK cells in spleen were present at higher frequency than after cps1-1 infection, which may correlate with loss of the mature cNK cell population." (PMID 27721814, 2016). "On the other hand, IL-15 SA treatment caused CD8+ T cell activation (~12% CD69 expression) post infection, which was significantly higher as compared to sham (5%) but not statistically different as compared to the vehicle treated burn wound infected group (~8%)." (PMID 26859674, 2016). "A CD69 deficiency enhances the inflammatory phenomenon in cases of infective diseases in which the inflammatory environment is essential for aggravating the infection." (PMID 25254368, 2014). "Early infection and destruction of intestinal CD4+ T cells appears to be selective for memory CD4+ T cells co-expressing CD69, which are likely much more susceptible to infection through expression of appropriate co-receptors (CCR5) and their increased state of activation." (PMID 22096538, 2011). "To assess whether infection resulted in a generalised activation of mucosal-associated B cells, we also measured expression of CD69 and CD86, two surface markers up-regulated on activated B cells." (PMID 20306466, 2010).
infection (continued). "Likewise, changes in CD4+ T cell activation state has also been reported to modulate HIV entry and infection susceptibility with CD4+ T cells expressing the early activation marker CD69 being preferential targets of HIV infection relative to naïve cells in both blood and tissue." (PMID 39872519, 2024). "Interestingly, analysis of the activation marker CD69, revealed that VZV infection was associated with a significantly higher proportion of CD69+ MAIT cells compared to mock infection in both the context of whole PBMCs and MAIT cells FACS sorted on the basis of CD69 expression." (PMID 37006246, 2023). "Moreover, infection with HIV-GFP reporter viruses that either lack Nef or expressed a mutated form of Nef in its SH3-binding domain suggested that Nef modulates the expression of CD69 on the surface of infected macrophages." (PMID 24341794, 2013). "CD69 expression by NK cells is induced by infection with different microorganisms, interferons, and tumour necrosis factor alpha, which promote release of proinflammatory cytokines." (PMID 39978117, 2025). "Expression of CD83 and CD69 was higher in adults compared to children when analyzing the total number of B cells contained in all infection-induced clusters highlighting the concordance with the CyTOF data." (PMID 40834853, 2025). "Administration of TLR4 or TLR3 agonists or intranasal infection of mouse-adapted influenza virus (H1N1) or coronavirus (MHV-A59) induced CD69 in lung ECs." (PMID 40617350, 2025). "H1N1 infection led to ∼ 25% of lung alveolar EC expressing CD69 in the loci of infection, which was almost reduced to background levels in the Cd69 ECKO mice." (PMID 40617350, 2025). "Although CD69+ S1+RBD+ BSM were noted post-infection and post-vaccination, the percentage of CD69+ cells among S1+RBD+ BSM was significantly higher in INF tonsils compared to VAC." (PMID 40964019, 2025). "TKS infection under permissive conditions prompted infiltration of activated T cells (CD11ahigh, CD69+, KLRG1+ and PD-1+), along with the recruitment of effector and resident memory T cells." (PMID 39794471, 2025). "The activation of these cells became even more evident at 5 dpi and more pronounced in lymphoid organs than in periphery blood in terms of CD69 expression after infection, which was shown in our previous study." (PMID 38419627, 2024). "In peripheral LN there was also a significant increase in NK cells expressing CD69 from the pre-infection timepoint (mean 6.81% range: 1.64%-14.98%) to 22DPI (mean 21.95% range: 3.32%-50.58%) (p-value = 0.0312), suggesting a potential cell redistribution." (PMID 39133756, 2024). "On the other hand, CD4+ cell depletion did not significantly affect B1 B cells, CD69+ B1 B cells, or expression of CD69 on B1 B cells 2 days post-infection." (PMID 38715601, 2024). "In both the liver and spleen, NK cells showed activation during infection, as evidenced by the increased expression of the CD69 surface marker." (PMID 39031850, 2024). "Our prospective study revealed a restoration of CD69 levels to near pre-infection levels 1 month after ART initiation." (PMID 38364104, 2024). "Most noticeably, the fraction of each immune cell type expressing CD317 and CD69 was substantially increased (q < 0.0001) upon infection or phagocytosis (iHA+sHA–) compared with uninfected cells (iHA–sHA–)." (PMID 38814732, 2024). "Both WT and TLR7 KO mice displayed similar increases in CD8+ cytotoxic T cells in response to infection; however, the proportion of these cells expressing CD69 was significantly lower in TLR7 KO mice." (PMID 39769461, 2024). "After primary infection, expression of CD69 and CD103 in NOH mice was lower compared to the later time point." (PMID 38961265, 2024). "Within two days of type I IFN-induced CD69 expression, infection of B cells within mediastinal lymph nodes induces upregulation of CD69 and the co-stimulatory surface molecule CD86, thereby regulating B cell egress from lymph nodes into the bloodstream." (PMID 38203508, 2023).